RN7SL521P (RNA, 7SL, cytoplasmic 521, pseudogene)
Gene: Miscellaneous RNA gene on chromosome 7 (149,125,690 to 149,125,986, reverse strand). Ensembl gene ENSG00000240877.
Homologues: Orthologues: chimpanzee Metazoa_SRP (99% identical), macaque Metazoa_SRP (94% identical). Paralogues in human: RN7SL2 (82% identical), Metazoa_SRP (82% identical), RN7SL1 (82% identical), RN7SL3 (80% identical), RN7SL7P (75% identical), RN7SL45P (75% identical), RN7SL732P (75% identical), RN7SL769P (75% identical), RN7SL493P (74% identical), RN7SL679P (74% identical), RN7SL118P (74% identical), RN7SL126P (74% identical), and 703 more.